PRKCB (protein kinase C beta)
Diseases named in the same sentence as PRKCB in open-access papers (continued):
Sharing a sentence is not in itself a finding about the gene and the disease.
Insulin resistance (8 papers, 2011 to 2024). Increased resistance towards insulin, that is, diminished effectiveness of insulin in reducing blood glucose levels. "Protein kinase C beta (PKCβ) activation may also explain the link between inflammation, ED, and insulin resistance in DM." (PMID 22347666, 2012).
lymphoma (8 papers, 2007 to 2025). A malignant (clonal) proliferation of B- lymphocytes or T- lymphocytes which involves the lymph nodes, bone marrow and/or extranodal sites. "PRKCB has also been reported to be included in the prognostic signature for adult T-cell leukemia/lymphoma and prostate cancer." (PMID 35615380, 2022). "Protein kinase Cβ (PRKCB) plays a role in autophagy regulation, CREBBP inactivation promotes the development of HDAC3-dependent lymphomas, and abnormal expression of Casein kinase 2α1 (CSNK2A1) is linked to neurological diseases and cancer." (PMID 34211501, 2021).
prostate carcinoma (8 papers, 2016 to 2026). A carcinoma that arises from epithelial cells of the prostate gland. "Aberrant expression of PRKCB is also linked to glioblastoma, breast and prostate cancer as well as PRKCE overexpression." (PMID 27144431, 2016). "In addition, androgen stimulation protein kinase C-beta (PKCβ) and protein kinase C related kinase 1 (PRK1) phosphorylate H3tre6 and 11 respectively in prostate cancer cells." (PMID 29541423, 2018).
COVID-19 (7 papers, 2020 to 2022). A disease caused by infection with severe acute respiratory syndrome coronavirus 2. "A significant downregulation of protein kinase C beta [P05771] in the COVID-19 group compared to controls was evidenced in our study, a finding that warrants further investigation." (PMID 36077551, 2022). "Seven core targets of vitamin A against COVID-19, including CAT, EGFR, ICAM1, IL10, MAPK1, MAPK14, and PRKCB, have been detected." (PMID 34335237, 2021). "Furthermore, seven core targets of VA against COVID-19, including MAPK1, IL10, EGFR, ICAM1, MAPK14, CAT, and PRKCB were identified." (PMID 32805728, 2020). "Besides, in silico models indicate that the mechanism of action of vitamin A against COVID-19 is carried out via modulation of gene expression of key proteins involved in inflammatory reaction and reactive oxygen species production (such as MAPKs, IL10, ICAM1, or PRKCB)." (PMID 35684054, 2022).
lupus (7 papers, 2015 to 2022). "PRKCB, as the locus of systemic lupus erythematosus, was observed to have upregulated mRNA expression in the peripheral blood mononuclear cells of patients with systemic lupus erythematosus." (PMID 34335821, 2021). "PRKCB enhancement might be a promising strategy to improve macrophage functions in lupus patients with LPS-tolerance from chronic infection." (PMID 30889825, 2019). "PRKCB might be considered a novel target for the treatment of LPS-tolerance in lupus." (PMID 30889825, 2019). "For example, Protein Kinase C-β, encoded by the PRKCB gene, recruits IKK into lipid rafts and is involved in B-cell receptor (BCR)-mediated NF-κB activation, and the SNP rs16972959 was shown to associate with systemic lupus erythematosus (SLE) in a Han Chinese population." (PMID 28095483, 2017).
chronic lymphocytic leukemia (6 papers, 2007 to 2025). "PRKCB, a member of the serine- and threonine-specific protein kinase C family, is crucial for B-cell receptor signaling and development, and its dysregulation has been associated with chronic lymphocytic leukemia." (PMID 41331166, 2025). "Among the alterations related to this signaling, PRKCB mutation is the only alteration associated with the prognosis A phase I trial using a selective PRKCB inhibitor for chronic lymphocytic leukemia is being conducted (NCT03492125)." (PMID 33918793, 2021).
glioblastoma (6 papers, 2008 to 2024). The most malignant astrocytic tumor (WHO grade IV). "Various drugs targeting PRKCB are associated with antioxidant effects, therapeutic benefits for relapsed glioblastoma multiforme, and preventive measures for vitamin E deficiency." (PMID 38707907, 2024). "Quisinostat induced upregulation of PRKCB, which is targetable by Enzastaurin (currently in glioblastoma treatment phase 3 trial)." (PMID 34996497, 2022).
lung adenocarcinoma (6 papers, 2014 to 2025). A carcinoma that arises from the lung and is characterized by the presence of malignant glandular epithelial cells. "FGF13 and PRKCB act as antioncogenes that inhibit tumor progression by modulating the immune functions in acute myeloid leukemia and lung adenocarcinoma." (PMID 38686055, 2024). "PRKCB was reported to be hypermethylated in lung adenocarcinoma stage I while hypomethylated in stage II, suggesting a potential of PRKCB hypermethylation assessment for NSCLC early detection." (PMID 28422739, 2017). "Methylation of PRKCB has been investigated in few types of malignancies, where a positive correlation was identified between methylation of two CpGs and gene expression by analyzing the TCGA dataset of lung adenocarcinoma." (PMID 34198725, 2021). "Genetic alterations of PRKCB have been reported in NSCLC, suggesting its involvement in the progression of lung adenocarcinoma." (PMID 41262895, 2025).
ovarian carcinoma (6 papers, 2015 to 2022). A malignant neoplasm originating from the surface ovarian epithelium. "Secondly, WNT9A, PRKCB, SGK1, and DUSP6 have been shown to promote or inhibit the development of ovarian cancer." (PMID 32331314, 2020).
Immunodeficiency (5 papers, 2008 to 2025). Failure of the immune system to protect the body adequately from infection, due to the absence or insufficiency of some component process or substance. "PRKCB is associated with immune cell infiltration, and increased PRKCB expression promotes increases in the numbers of naive B cells, M1 macrophages, and other immune cells, while decreased PRKCB expression leads to severe immunodeficiency and memory impairment." (PMID 39324544, 2024). "Conversely, underexpression of PRKCB leads to severe immunodeficiency." (PMID 40948939, 2025).
Alzheimer disease (4 papers, 2020 to 2025). A progressive, neurodegenerative disease characterized by loss of function and death of nerve cells in several areas of the brain leading to loss of cognitive function such as memory and language. "PRKCB is a member of the serine- and threonine-specific protein kinases family, and it has been associated with various processes, including, among others, immune response homeostasis and initiation, lipid peroxidation and induced ferroptosis and Alzheimer’s disease pathogenesis." (PMID 36835433, 2023). "Specifically, RASGRP1, PRKCB, and NFATC1 are implicated in both RA and Alzheimer’s disease, suggesting therapeutic convergence." (PMID 40839671, 2025). "RASGRP1 and PRKCB displayed elevated expression in brain tissue, suggesting a genetic connection between RA and neuroinflammatory diseases such as Alzheimer’s disease." (PMID 40839671, 2025). "PRKCB overexpression, as seen in our results, has been previously reported in advanced neurodegenerative stages [i.e., PD and Alzheimer’s disease (AD)]." (PMID 40948939, 2025). "The purpose of this study was to investigate the potential roles of protein kinase C beta (PRKCB) in the pathogenesis of Alzheimer’s disease (AD)." (PMID 33186918, 2020). "Notably, RASGRP1 and PRKCB exhibit elevated expression in brain cells, a finding that aligns with their identification as novel biomarkers for Alzheimer’s disease." (PMID 40839671, 2025). "In addition to their role in RA, certain novel targets, such as RASGRP1 and PRKCB exhibit high expression in brain tissues, implicating them in neuroinflammatory processes and suggesting genetic overlap between RA and Alzheimer’s disease." (PMID 40839671, 2025).
B cell lymphoma (4 papers, 2007 to 2022). "The PRKCB mutation is also found in DLBCL, a B-cell lymphoma." (PMID 33918793, 2021). "Similar to the PRKCB inhibitor, effect of a MALT1 inhibitor for B-cell lymphoma is also under evaluation (NCT03900598) and it may also be effective for ATLL." (PMID 33918793, 2021).
major depression (4 papers, 2022 to 2025). "Further findings highlight that PRKCB expression is downregulated in the peripheral blood mononuclear cells of depressed patients, with specific SNPs in PRKCB showing association with major depression." (PMID 39684694, 2024). "The PRKCB gene expression in peripheral blood mononuclear cells (PBMC) was shown to be down-regulated in depressed patients, and an association with a combination of three SNPs at PRKCB gene with major depression was reported." (PMID 35504874, 2022). "RNA editing modifications were analyzed using a panel of eight genes (CAMK1D, GAB2, IFNAR1, KCNJ15, LYN, MDM2, PDE8A, PRKCB) that we previously identified and whose editing combinations were suggested as biomarkers to distinguish BD from unipolar depression and subcategories of BD patients." (PMID 39684694, 2024). "Furthermore, GNAO1 is closely related to epileptic encephalopathy and neurological dysfunction, PRKCB exerts a regulatory effect on neuronal function, and GRIA2 is closely related to status epilepticus and depression." (PMID 36533076, 2022).
renal fibrosis (4 papers, 2014 to 2025). A final common manifestation of a wide variety of chronic kidney diseases characterized by glomerulosclerosis and tubulointerstitial fibrosis. "The active protein kinase C beta (PKCβ) pathway contributes to renal fibrosis in hyperuricemia boosted mice." (PMID 35162887, 2022).
cervical cancer (3 papers, 2017 to 2022). A primary or metastatic malignant neoplasm involving the cervix. "The genes encoding VGEF, RRAS2, PRKCB, RASGRP, and PDGFB involved in the six cell-signaling pathways are not currently reported in cervical cancer; however, they were reported as overexpressed in other carcinomas, suggesting their participation in carcinogenesis." (PMID 30696040, 2019).
hepatocellular carcinoma (3 papers, 2022 to 2025). A malignant tumor that arises from hepatocytes. "O-GlcNAc-modified RACK1 enhances ribosome binding and interaction with PRKCB, thereby increasing the translation of potent oncogenes in hepatoma cells." (PMID 38993567, 2024).
lung carcinoma (3 papers, 2016 to 2024). "Various studies have shown that the expression of PRKCB is significantly increased in a variety of tumour cells such as lung cancer, nasopharyngeal carcinoma, human non-small cell carcinoma, and other malignant tumour cells." (PMID 39765731, 2024).
Stroke (3 papers, 2015 to 2025). Sudden impairment of blood flow to a part of the brain due to occlusion or rupture of an artery to the brain. "Network pharmacology analysis revealed eight intersecting targets, including MAPK1, PRKCB, HDAC1, and serotonin receptors, associated with neuroinflammatory and vascular pathways in strokes." (PMID 41011194, 2025). "For example, it has been reported that inhibition of PRKCB increased BBB permeability during hyperglycemic stroke and prevents edema formation in vivo." (PMID 26101539, 2015). "Eight common genes were found across all three compounds and stroke: MAPK1, PRKCB, PRKCG, HDAC1, HTR1A, HTR2A, HTR2C, and HTR7." (PMID 41011194, 2025).
viral infection (3 papers, 2017 to 2024). "TNFAIP3, ULBP1 and TIAM1 were consistently down-regulated by viral infection, while CCL8, CCL11, CXCL11, NCF2, CSF3 and PRKCB were significantly up-regulated after infection." (PMID 28938587, 2017).
Cerebral ischemia (2 papers, 2017 to 2025). Restriction of arterial blood supply to the brain associated with insufficient oxygenation to support the metabolic requirements of the tissue. "MAPK1 and the PKC isoforms PRKCB and PRKCG have been shown to mediate pro-apoptotic responses, oxidative stress, and neuroinflammation following cerebral ischemia." (PMID 41011194, 2025).
dementia (2 papers, 2020 to 2024). Loss of intellectual abilities interfering with an individual's social and occupational functions. "According to the gene data of all samples, the mean expressions of PRKCB in 97 AD patients (10.08 ± 1.16) were significantly lower than those in 98 non-dementia controls (11.07 ± 0.95; P < 0.001)." (PMID 33186918, 2020). "Four protective proteins (PLEK, DAPP1, CSK and CASP3) that decreased postinfection in the BLSA were significantly decreased in dementia cases in the ARIC study, with several other protective proteins (EIF4A1, DSG1, PIK3CG, PRKCB and LYN) showing similar trends." (PMID 39143319, 2024).
epilepsy (2 papers, 2019 to 2021). A brain disorder characterized by episodes of abnormally increased neuronal discharge resulting in transient episodes of sensory or motor neurological dysfunction, or psychic dysfunction. "Genes most frequently shared among class 1 modules (such as DLG4, GRIN2A, PRKCB, and SNAP25) have been associated with epilepsy, synaptic function, and neuronal processes." (PMID 31653223, 2019). "In addition, we found that miR-484 upregulation is accompanied by the epilepsy progression via inhibition of the three hub gene expression (CTD-3193O13.9, EFNA5, and PRKCB)." (PMID 34722763, 2021).
Huntington disease (2 papers, 2022). Huntington disease (HD) is a rare neurodegenerative disorder of the central nervous system characterized by unwanted choreatic movements, behavioral and psychiatric disturbances and dementia. "In contrast, the PRKCB low expression related gene sets were rich in Huntington's disease, oxidative phosphorylation, purine metabolism, pyrimidine metabolism, and base excision repair." (PMID 35567329, 2022). "Three of these were downregulated in Huntington’s disease compared with WT mice under SH conditions (MAST3, PRKCB and CAMK4) and could therefore be responsible for changes in the phosphoproteome observed between these two groups." (PMID 36523271, 2022).
lung disease (2 papers, 2018 to 2020). "However, only CHP2 and PRKCB in the chr16 region are consistently associated with CF lung disease by expression imputation." (PMID 33253230, 2020).
mastitis (2 papers, 2024). Inflammation of breast tissue during lactation or postpartum due to an obstructed duct or infection. "Previous studies have shown that DEPs, such as SLC34A2, PRKCB, FTH1, and MAPK1, could be putative biomarkers for mastitis." (PMID 38731279, 2024).
mesothelioma (2 papers, 2011 to 2015). A usually malignant and aggressive neoplasm of the mesothelium which is often associated with exposure to asbestos. "We data-mined on mesothelioma datasets the expression of PKCβ (PRKCB), the favoured RACK1 partner." (PMID 26462016, 2015).
pneumonia (2 papers, 2020 to 2022). An acute, acute and chronic, or chronic inflammation focally or diffusely affecting the lung parenchyma, caused by an infection in one or both of the lungs (by bacteria, viruses, fungi, or mycoplasma.). "Some evidence indicates that PRKCB overexpression is associated with the development of pneumonia via activation of the NF-κB pathway." (PMID 32805728, 2020). "In conclusion, we discover that NETosis is critical in SCAP and highlight H4C15, H3-5, DNASE1, and PRKCB as promising therapeutic targets for severe pneumonia." (PMID 36466920, 2022).
rectal cancer (2 papers, 2017 to 2021). A primary or metastatic malignant neoplasm that affects the rectum. "built a multi‐gene mRNA model using PRKCB and other related mRNAs, which showed a good ability (AUC:0.846) to predict the response of preoperative chemoradiotherapy for rectal cancer." (PMID 34613665, 2021). "According to literature validation, we detected some rectal cancer‐related mRNAs including PRKCB, NCAM1, ZEB1, PCDH7, Cav1 and FGF2 in the subnetwork." (PMID 34613665, 2021). "For example, PRKCB was found to be involved in a biomarker model, which could predict rectal cancer response to preoperative chemoradiotherapy." (PMID 34613665, 2021).
asthma (1 paper, 2023). "CXCL10 was upregulated in asthma and LCP1, CCR1, PRKCB, IRAK2, LILRA1, and ZEB1 were significantly upregulated in COPD patients." (PMID 36829591, 2023).
Autoimmunity (1 paper, 2022). The occurrence of an immune reaction against the organism's own cells or tissues. "Altogether, we found deletion of genes associated with autoimmunity mediated early hematopoiesis (e.g. ZEB2) and influenced the inflammatory potential (e.g. ICAM1, LSP1 and PRKCB) of iPSC-derived myeloid cells, coinciding with the expected phenotype." (PMID 35610203, 2022).
bipolar disorder (1 paper, 2024). A disorder of the brain that causes unusual shifts in mood, energy, activity levels and the ability to carry out day-to-day tasks. "For bipolar disorder, we examined the protein encoded by PRKCB." (PMID 38671846, 2024). "For bipolar disorder, genetic variation in the vitamin E (PRKCB in ROSMAP, OR = 0.248, 95% CI = 0.152–0.403, p = 1.24 × 10−5; rs4967960 was excluded due to the F statistic being less than 10) target was related to an increased risk of BD." (PMID 38671846, 2024).
cholangiocarcinoma (1 paper, 2023). A carcinoma that arises from the intrahepatic biliary tree (intrahepatic cholangiocarcinoma) or from the junction, or adjacent to the junction, of the right and left hepatic ducts (hilar cholangiocarcinoma). "A cfDNA analysis of cholangiocarcinoma patients and healthy sex- and age-matched controls revealed differentially methylated regions (DMRs) in four genes (HOXA1, PRKCB, CYP26C1, and PTGDR) in CCA patients." (PMID 37568696, 2023).
cognitive decline (1 paper, 2024). "We showed that a subset of these proteins was associated with cognitive decline and levels of AD and neurodegeneration plasma biomarkers, including PIK3CG, PACSIN2 and PRKCB." (PMID 39143319, 2024).
Crohn disease (1 paper, 2025). A gastrointestinal disorder characterized by chronic inflammation involving all layers of the intestinal wall, noncaseating granulomas affecting the intestinal wall and regional lymph nodes, and transmural fibrosis. "Seven shared risk genes (CD40, PTPN22, CD226, BATF, PRKCB, RasGRP1, and PTPN2) are involved in cytokine pathways linked to Crohn’s disease." (PMID 40839671, 2025).
escherichia coli infection (1 paper, 2013). Infection with the organism Escherichia Coli. "PRKC (including PRKCA and PRKCB), along with VAV (VAV2 and VAV3) genes also feature in various high ranking immunological pathways including T cell signaling, Pathogenic Escherichia Coli Infection and Natural Killer Cell Mediated Cytotoxicity." (PMID 24278029, 2013).
Ewing sarcoma (1 paper, 2021). A small round cell tumor that lacks morphologic, immunohistochemical, and electron microscopic evidence of neuroectodermal differentiation. "PRKCB inhibition significantly increased apoptosis in Ewing sarcoma cells and prevented tumor growth in vivo." (PMID 33653335, 2021).
head-neck squamous cell carcinoma (1 paper, 2021). "The promoter hypermethylation of PRKCB causing its downregulation was validated by experimental results and higher PRKCB expression was associated with longer overall survival in head-neck squamous cell carcinoma, suggesting the potential of PRKCB as a promising disease biomarker for NPC." (PMID 33403044, 2021).
heroin addiction (1 paper, 2016). "In this analysis, we found that the 4-gene model that contained JUN, CEBPB, ENO2, and PRKCB genes had an accuracy rate of 85.5% in the prediction of heroin addiction in this dataset." (PMID 27495086, 2016). "Our classification analysis identified JUN, CEBPG, ENO2, and PRKCB as the key gene expression signatures for a subdivision of heroin dependence and controls." (PMID 27495086, 2016).
kidney cancer (1 paper, 2024). Primary or metastatic malignant neoplasm involving the kidney. "Our study suggests that Resibufogenin may be used as a targeted inhibitor of PRKCB in the treatment of kidney cancer, which provides theoretical support for the clinical application of Resibufogenin." (PMID 39765731, 2024).